MIR138-1 (microRNA 138-1)
Synonyms: hsa-mir-138-1; MIRN138-1; mir-138-1
Gene: MicroRNA gene on chromosome 3 (44,114,212 to 44,114,310, forward strand). Ensembl gene ENSG00000207954.
Gene Ontology:
Biological process: miRNA-mediated post-transcriptional gene silencing
Cellular component: RISC complex
Homologues: Orthologues: chimpanzee MIR138-1 (100% identical), rat Mir138-1 (92% identical), guinea pig MIR138-1 (84% identical), pig ssc-mir-138 (80% identical), dog MIR138-1 (77% identical), tropical clawed frog xtr-mir-138 (70% identical), zebrafish dre-mir-138 (64% identical), rabbit MIR138-1 (59% identical). Paralogues in human: MIR138-2 (56% identical).